TIGIT (T cell immunoreceptor with Ig and ITIM domains)
Diseases named in the same sentence as TIGIT in open-access papers (continued):
Sharing a sentence is not in itself a finding about the gene and the disease.
cancer (continued). "Various cancers have shown upregulation of CD155, which may bind to TIGIT and CD96 in order to evade NK cell-mediated antitumor immunity by eliciting NK cell inhibition, including suppression of granule polarization and IFN-γ production." (PMID 32640575, 2020). "Using a 10 color flow cytometry panel, we assessed the surface expression of six NK cell receptors, which are known to activate (NKG2D and DNAM-1) or inhibit (NKG2A, PD-1, TIGIT, and TIM-3) NK cell effector functions in a cohort of 16 healthy donors and 20 cancer patients." (PMID 32508837, 2020). "The role of TIGIT and CD96 in immune responses to cancer has been thoroughly reviewed elsewhere." (PMID 33613552, 2020). "Like TIGIT and PD-1, NKG2A, and the inhibitory subset of KIRs prevent excessive inflammation but may interfere with productive anti-cancer activity." (PMID 31456796, 2019). "In this paper, we found that aspirin attenuates cancer cell proliferation and induces CRC cell apoptosis by down‐regulating the expression of T cell Ig and ITIM domain receptor (TIGIT), which provides new evidence for the application of aspirin in cancer treatment in clinics." (PMID 31090213, 2019). "To comprehensively investigate the immunoinhibitory pathways in T cells, we used FACS to analyze the surface expression of eight IRs (PD-1, Tim-3, BTLA, KLRG-1, TIGIT, 2B4, CD160, and CTLA-4) on T cells from peripheral blood and tumors isolated from 131 cancer patients." (PMID 31709176, 2019). "The axis of DNAM-1 and TIGIT/PVRIG/TACTILE, in which shared ligands and different receptor-ligands affinities regulate the immune response, represents a novel checkpoint for improving immune responses against cancer." (PMID 31234588, 2019). "Robust inflammation present in the HPV-active tumors, along with higher expression of immune checkpoint inhibitor targets TIGIT, CTLA4 and PDL-1, suggest that immune checkpoint inhibitor therapy may be a productive approach for these virally driven cancers." (PMID 28077784, 2017). "The expression of TIGIT on cancer patients’ (n = 35) circulating CD8+ T cells (not circulating CD4+ T cells) was significantly lower than that of normal donors (n = 10)." (PMID 27577071, 2016). "TIGIT is also elevated on CD4 and CD8 T cells in the blood of cancer patients." (PMID 26347741, 2015). "Finally, we checked for the effect of TAK-981 on (i) TIGIT (inhibitory receptor) and DNAM1 (activating receptor), which compete for binding to PVR and Nectin-2 on cancer cells, and (i) LFA1, which binds to ICAM-1 and stabilizes NK interaction with their target cells." (PMID 40661051, 2026). "In addition, data from several phase III clinical trials support a role for TIGIT in other cancers, and blocking TIGIT in non-advanced tumors can be attempted." (PMID 40890162, 2025). "Additionally, interactions between FOXP3high/+ Tregs and cancer cells may be involved in Treg mobilization (CXCR6/CXCL16) and activity (TIGIT/PVR)." (PMID 40164596, 2025). "Ongoing research into predictive biomarkers for anti-TIGIT ICI and the development of anti-TIGIT antibodies with optimal immunologic activity and therapeutic efficacy are critical for advancing TIGIT-targeting therapies in the treatment of ESCC and other cancers." (PMID 39847233, 2025). "On the other hand, expression of TIGIT was detected only in T cells but not in cancer cells." (PMID 40371640, 2025). "In recent years, with the discovery of the considerable therapeutic potential of cancer immunotherapy, researchers have developed new immune checkpoint targets, such as TIM3, lymphocyte activation gene 3 (LAG3), and tyrosine-based inhibition motif domain (TIGIT)." (PMID 40362568, 2025). "When we believe that immunotherapy could be a panacea in cancer care, we combine anti-PD1/L1 with another CPI (such as anti-CTLA-4, anti-IDO1, anti-TIGIT) and with agents that target immune factors (e.g., IL-2) and effectors (e.g., dendritic cells, T cells, macrophages, NK cells), etc." (PMID 38539487, 2024).
cancer (continued). "Suppose PDL1 (like LAG3) is not only a CPI but also a stemness marker (unlike other CPI), could that explain why anti-PD1/L1 (and anti-LAG3) is a better anti-cancer treatment compared with those other CPI (e.g., anti-CTLA4, anti-IDO1, anti-TIGIT), which are bona fide immunotherapy?" (PMID 38539487, 2024). "Besides, the TIGIT- NECTIN2 interaction between T cells and cancer cells was found in MBC samples." (PMID 37696831, 2023). "Based on these studies, we postulate that one of the factors limiting the success of TIGIT antagonism in the treatment of cancer could be due to the lack of synergistic CD226 co-stimulation." (PMID 36944702, 2023). "Lower TIGIT/LAG-3 binding affinities of these antibodies compared to their benchmarks could also prevent them from inducing ADCC/ADCP of effector T cells while maintaining their potency in promoting T cell activation and cancer cell killing." (PMID 37332070, 2023). "In fact, high LAG3 and TIGIT expression in infiltrated tumors could be indicative of a specific inflammatory milieu triggering LAG3 upon CD8+ T cell infiltration and sensitizing these cells to exhaustion signals from mesenchymal cancer cells." (PMID 38086828, 2023). "More importantly, the expression of PIK3R4 in DLBCL was correlated with the immune cell content in the cancer microenvironment, CD8(+) T-cell and neutrophil infiltration and the levels of several immune checkpoint molecules, including BTN3A2, BTN3A1, PRF1, CXCL9, PDCD1, and TIGIT." (PMID 37670973, 2023). "Our data show that GB265, GB266, and GB266T have superior performance to these antibody combinations in assays that mimic the general characteristics of the TME, and could represent a better approach to target the PD-1, TIGIT and LAG-3 immune checkpoints in immunotherapy of cancers." (PMID 37332070, 2023). "Based on the number of new trials started in recent years, emerging therapies of interest for the future may lie in combinations with approved therapies such as PARP inhibitors, as well as rising IO targets and agents such as TIGIT, TGFβ/TGFR, TLRs, oncolytic viruses, and cancer vaccines." (PMID 36765640, 2023). "Multiple studies have found that TIGIT may regulate the effector function of antitumor and antiviral CD8+ T cells effector function via participating in the TIGIT-CD96-CD112R-CD226 axis in the cancer immunotherapy." (PMID 35320940, 2022). "In this study, high TIGIT expression promoted the infiltration levels of CD8 T cells, M1 macrophages, naive B cells, activated memory CD4 T cells, Tregs and activated NK cells while inhibiting the infiltration levels of activated dendritic cells and mast cells in most of the cancers included." (PMID 36211383, 2022). "Furthermore, although cancer therapeutics has been dominated by PD-1 and CTLA-4 targeting antibodies, many other checkpoints with the potential to impinge on the clinical course of PDAC, including TIGIT, Tim3, Lag3 and CD39, have been identified." (PMID 33917832, 2021). "Thus, taken together, these data indicate that the therapeutic targeting of the TIGIT pathway was effective in septic animals with preexisting malignancy but not in PH septic animals." (PMID 34100383, 2021). "However, the correlations of TIGIT expression with MSI and TMB didn’t coincide in some of the same cancer types, which could be explained by 2 reasons." (PMID 34795387, 2021). "Although the most advanced knowledge has been generated around the therapies targeting PD-1/PDL-1 or CTLA-4, there are multiple other important pathways that may impact the immune response to cancer involving many genes, in particular LAG-3, TLR-4, VISTA, TIM-3, TIGIT, ICOS, OX40, and GITR5." (PMID 33911192, 2021). "Extensive preclinical murine cancer models and clinical development efforts have been undertaken for a number of co-inhibitory, or immune checkpoint, receptors that have been characterized as identifying exhausted T cells, including CTLA-4, PD-1, LAG-3, TIM-3, and TIGIT." (PMID 30858925, 2019).
cancer (continued). "Interestingly, disease-associated TEX in chronic infection were further characterized by co-expression of inhibitory receptors TIGIT and 2B4 (as well as some KLRG1 and CD160) while in cancer, TEX more frequently exhibited higher expression of CTLA-4, Lag-3, and CD39." (PMID 32038613, 2019). "Interestingly, TIGIT or CD155 blockade with antibodies restores NK and CD8+ T cell function further supporting that targeting TIGIT-CD155 interaction could be useful for immunotherapy of cancer." (PMID 31234588, 2019). "Non-redundant checkpoints increased in PD-1-resistant cancers include LAG-3, TIGIT, TIM-3, and VISTA." (PMID 41584608, 2025). "In contrast, no clinical evidence is available for anti-LAG3, anti-TIGIT, anti-BTLA, anti-ICOS and anti-IDO1 antibodies in MSI-H cancers, but clinical trials are ongoing." (PMID 38254772, 2024). "Our analysis of LRRC59 in relation to pan-cancer immune infiltration and immunotherapy reveals a positive correlation between LRRC59 expression and TIM-3 and TIGIT, while a negative correlation with LAG-3 and PDCD1." (PMID 38738999, 2024). "While there are currently no anti-TIGIT clinical trials in GBM, some agents have been examined in other cancers." (PMID 34359588, 2021). "Along this line, it would be important to assess whether a co-blockade of TIGIT and HIF-1α is as effective as the blockade of TIGIT and PD-1 as a therapeutic possibility for those cancers which are not PD-L1 positive." (PMID 36874131, 2023). "Because PVR and TIGIT proteins can be found in soluble forms, we quantified soluble PVR protein levels in bone marrow plasma from patients with MM, MGUS, and patients without cancer." (PMID 35625835, 2022). "Thus, we investigated the potential influence of NTF3 expression on cancer immunotherapy and found a positive correlation between NTF3 expression and immune checkpoints, including PD-L1, TIGIT, and TIM-3, but not CTLA4." (PMID 34938753, 2021). "It was identified that HAVCR2 had positive infiltration scores in all cancer types, whereas a negative infiltration score was noted for CXCL13 (in LGG and DLBCL), LAG3 (in DLBCL and AML), LAYN (in CHOL, KICH, AML, LGG, PCPG, THCA and UCS), PDCD1 (in DLBCL, AML and THYM) and TIGIT (DLBCL and AML)." (PMID 40076932, 2025).
infection (49 papers, 2016 to 2026). The state of being infected such as from the introduction of a foreign agent such as serum, vaccine, antigenic substance or organism. "Decreased frequencies of naïve CD4 and CD8 T cells (p=0.016 and p=0.038, respectively) and increased frequency of CD4 CM and EM TIGIT+ T cells (p=0.022) were associated with development of infection." (PMID 40475763, 2025). "We observed that increased frequencies of CD4 CM and CD4 EM TIGIT+ T cells pre-transplant were associated with infection (p=0.014 and p=0.018, respectively), even with age correction (Pre)." (PMID 40475763, 2025). "Increased frequency of EM TIGIT+ CD4 T cells demonstrated a trend towards association with infection (p=0.18)." (PMID 40475763, 2025). "Our findings revealed that in vivo infection of C. albicans in TIGIT-KO mice showed more survival and less body weight loss compared with the WT group." (PMID 39109867, 2024). "Our results establish the association between infection, T-cell homeostasis, and expression of PD-1 and TIGIT in long-lived CD4 T-cell subsets prior to ART with CD4 T-cell recovery and HIV persistence on-ART." (PMID 34449812, 2021). "Therefore, we conformed that CD4+T cells exerted predominant influence on anti-infection responses when loss of TIGIT." (PMID 38545097, 2024). "The observation that TIGIT expression is associated with immunosuppression start, lymphodepleting induction, and infection therefore suggests that upregulation of this marker may be an important pathway underlying infection vulnerability due to immunosuppression." (PMID 40475763, 2025). "Specifically, we show that TIGIT induces Areg in a Blimp-1-dependent manner, activating a tissue repair program in Treg cells that is essential for limiting pathology during infection." (PMID 41094201, 2025). "Here, we identified HIF1α and Blimp-1 as key regulators of Areg in Treg cells during infection, with HIF1α acting independently of TIGIT." (PMID 41094201, 2025). "Next, we employed the TIGIT blockade antibody (tiragolumab) to block the TIGIT pathway in CD8+ T cells from PGs during the chronic infection phase (133 days post-infection)." (PMID 40637373, 2025). "The frequency of TIGIT-expressing cells among splenic CD4+ T cells increased from weeks 2–4 post infection." (PMID 40526725, 2025). "TIGIT blockade alone or combined blockade with PD-1 can partially restored T cell function against infection." (PMID 40526725, 2025). "In particular, CD8+ T cells coexpressing the checkpoint molecules PD1, CTLA4, and/or TIGIT were diminished by breakthrough infection in pregnant individuals, and this effect was primarily driven by the Tcm subset of CD8+ T cells." (PMID 40693463, 2025). "Specifically, ECs demonstrated significantly low-level BTLA expression in CD4+ T cells (21, 49, 84, and 133 days post-infection), as well as diminished TIGIT expression in CD8+ T cells (49, 84, and 133 days post-infection) compared to PGs." (PMID 40637373, 2025). "Similar to the situation in blood, the upregulation of TIGIT expression in lung lesions has also been seen in a variety of infections." (PMID 40526725, 2025). "Similar to other co-inhibitory receptors, TIGIT is expressed after T cell activation, resulting in its upregulation during infections and sustained expression on exhausted T cells in chronic infections." (PMID 41094201, 2025). "Areg-producing Treg cells present upon infection are clonally expanded, and both TIGIT and TCR signaling are necessary for Areg induction by in vivo-primed T cells." (PMID 41094201, 2025). "Together, these findings indicate that Areg induction in Treg cells is highly context dependent, with combined TCR and TIGIT signaling being critical during infection." (PMID 41094201, 2025). "Together, these findings demonstrate that TIGIT can act as a mediator of tissue repair upstream of Areg and that its expression is essential for infection-induced Areg production." (PMID 41094201, 2025).
infection (continued). "TIGIT is expressed at high levels on terminal differentiated T cells in chronic LCMV infection and tumors, and the PD1+TIGIT+ phenotype is normally linked with hyporesponsive CD8+ T cells." (PMID 38533515, 2024). "The expression of PD-1 and TIGIT on CD4+ T cells at 2-4 weeks post-infection were variable and uncorrelated with adaptive immunity." (PMID 39355257, 2024). "In splenocytes, an elevated percentage of T helper CD4+, T cytotoxic CD8+, and NK cells was noted in both WT and TIGIT-KO mice following infection." (PMID 39109867, 2024). "Among blood lymphocytes, only the percentages of NK cells were increased in both WT and TIGIT-KO mice following infection with C. albicans." (PMID 39109867, 2024). "No change in CD4+ and CD8+ T cell percentages was observed after the infection of both WT and TIGIT-KO mice while NK cell percentages isolated from kidneys of infected WT and TIGIT-KO groups were elevated." (PMID 39109867, 2024). "Remarkably, a higher percentage of CD8+ T cells was noted in TIGIT-KO mice compared to their WT control group, whereas reduced CD8 cytotoxic T cell and NK cell percentages were observed in both WT and TIGIT-KO mice following infection with C. albicans." (PMID 39109867, 2024). "An analysis of the NK cell transcriptome sequencing data showed that the mRNA expression of the inhibitory receptor TIGIT on NK cells was significantly higher at 4 and 6 weeks post infection than that of other time points." (PMID 36930687, 2023). "The levels of inhibitory receptors including LAG-3, PD-1, and TIGIT all increased on NK cells after infection and were partially reduced in mice receiving ART." (PMID 36282589, 2022). "TIGIT blockade significantly reduced mortality and fungal burden during infection with the WT strain." (PMID 35513379, 2022). "In a RA mouse model induced by type-II collagen, TIGIT expression was upregulated in vivo by lentivector infection." (PMID 35720417, 2022). "Surprisingly, TIGIT blockade during C. albicans als6Δ/Δ infection even led to a paradoxical effect as it increased the fungal burden relative to the untreated mice." (PMID 35513379, 2022). "Overexpression of TIGIT by lentivector infection of human CD4+T cells, the cell proliferation, cytokines secretion (IL-12, IFN-γ, and TNF-α), and T-bet expression were significantly hindered whereas IL-10 production was enhanced." (PMID 35720417, 2022). "By the 7th day after infection, the splenic structure of infected mice was completely destroyed, and the relative expression of TIGIT increased significantly, while T. gondii was still proliferating." (PMID 33629951, 2021). "On the 7th day after infection, the expression of TIGIT in PBMCs and the spleen was significantly upregulated, eventually leading to immune failure and death." (PMID 33629951, 2021). "At the same time, splenic TIGIT+TCM cells were activated and transformed into TIGIT+TEM cells during the infection, and the cytotoxicity of TIGIT+ T cells was reduced in the later stage of infection." (PMID 34421855, 2021). "Studies have shown that the expression of TIGIT on T cells increased after infection with Echinococcus multilocularis, Plasmodium berghei or Schistosoma japonicum, and was negatively correlated with the immune function of T cells." (PMID 33629951, 2021). "As an immunosuppressive receptor, T-cell immunoglobulin and immunoreceptor tyrosine-based inhibitory motif domain (TIGIT) play a critical part in cellular immune regulation mediated by pathogen infection." (PMID 34421855, 2021). "From the 3rd day after infection, the expression of TIGIT in PBMCs and spleens of the infected group was significantly higher than in the control group, and the down-regulation of CD226 was also observed at the same time point." (PMID 33629951, 2021). "The MFI of TNF-α released by TIGIT+NK and TIGIT−NK cells in the first, third and twelfth month of infection was lower than that in HIV-1-negative donors." (PMID 33717085, 2021).